CD248 (CD248 molecule)
Diseases named in the same sentence as CD248 in open-access papers (continued):
Sharing a sentence is not in itself a finding about the gene and the disease.
tumor (continued). "Conversely, others have shown that the ectodomain of CD248 does interact with components of the ECM, including collagen, fibronectin and Mac-2 BP/90 K, and also participates in promoting tumor growth by modulating cellular adhesion and migration and promoting the release of MMP-9." (PMID 21549007, 2011). "Regrettably, there have been no reports on CAR-T therapy using other CD248-specific antibodies, which might also be effective for tumor-targeting therapy." (PMID 40276611, 2025). "Recent work detailing blockade with a CD93 mAb has led to interesting and promising results toward tumor vessel normalization rather than depletion as seen in antibody-directed binding to other group XIV CTLDs such as CD248 and CLEC14a as will be discussed in subsequent sections." (PMID 38468017, 2024). "To characterize a possible CD248 involvement in NSCLC cisplatin chemoresistance, we injected cisplatin (2 mg/kg) into CD248fl/flfsp‐1+/+ (WT) or CD248fl/flfsp‐1cre/+ (cKO) mice with Lewis's xenografts, measured the tumour volume, and generated a tumour growth curve." (PMID 38396325, 2024). "Mice lacking CD248 exhibit reduced tumor volume and vessel density." (PMID 37686288, 2023). "This led the authors to describe CD248 as a marker for tumour endothelium, although it could not be detected in cultured human umbilical vein endothelial cells (HUVEC)." (PMID 31287944, 2019). "Since elevated CD248 is associated with tumorigenesis, we tested whether TGFβ could suppress CD248 in tumor cell lines as effectively as in the healthy non-cancerous cells examined above." (PMID 24555435, 2014). "CD248 promotes tumorigenesis, while lack of CD248 in mice confers resistance to tumor growth." (PMID 24555435, 2014). "The findings indicate that the cytoplasmic domain of CD248 participates in the suppression of SM22α expression, providing a mechanism to help explain reduced stromal cell activation, migration and MMP-9 release and thus, less tumor expansion in the CD248CyD/CyD mice." (PMID 21549007, 2011). "Moreover, the same tumor does not necessarily progress in the same CD248-dependent manner in different anatomical sites." (PMID 21549007, 2011). "We show that lack of the cytoplasmic domain of CD248 in transgenic mice results in reduced tumor growth, with alterations in fibroblast signaling via TGF-β, PDGF-BB, and Notch pathways, and establishment of a pattern of gene expression favoring tumor suppression." (PMID 21549007, 2011). "Although the upregulation of CD248 was associated with tumor angiogenesis and metastasis, the upregulation of CD248 in the dry fasted serum at the end of 4-week DDDF is likely due to physiological angiogenesis rather than pathological tumor angiogenesis observed in several cancers." (PMID 40551123, 2025). "Further, upregulation of selectins and CD93, CD248, and CLEC14a on tumor ECs prompt investigation as to whether group XIV CTLDs can serve as a mediator or master regulator of the activated EC phenotype in the face of tumor-derived signals as is described for E-selectin." (PMID 38468017, 2024). "Since CD248 expression in CAFs has previously been reported, when coupled with CD248-related signatures significantly enriched in the stroma and ECM pathways, we suspected that the upregulation of CD248 might correlate with the CAF-mediated tumor-promoting effect." (PMID 34970489, 2021). "In vivo results showed that, regardless of the tumor type of origin, tumorspheres from both CD31+ CD105+ cells and CD146+ CD248+ cells were able to generate tumors that killed the host." (PMID 31267022, 2019).
cancer (54 papers, 2011 to 2025). A tumor composed of atypical neoplastic, often pleomorphic cells that invade other tissues. "High expression of CD248 was significantly associated with poor overall survival in several types of cancer, including GBM (HR = 1.6, P = 0.012), KIRP (HR = 1.9, P = 0.049), LGG (HR = 3.1, P < 0.001), and LUSC (HR = 1.4, P = 0.023)." (PMID 40276611, 2025). "We also confirmed that CD248 expression was positively associated with CAFs infiltration in pan-cancer." (PMID 40276611, 2025). "Non-small cell lung cancer (NSCLC)-originating cancer-associated fibroblasts (CAFs) expressing CD248 regulate interaction with immune cells to accelerate cancer progression." (PMID 38906929, 2024). "Cancer-associated fibroblasts (CAFs) express endosialin (CD248/TEM1) and interact with CD68, inducing the recruitment of Mφ." (PMID 37663266, 2023). "CD248 is a marker of certain tumors and cancer-associated fibroblast (CAF) and crosslinks fibronectin and collagen in a membrane-associated context." (PMID 36714146, 2022). "Independent studies have found CD248 mRNA or protein to be highly associated with multiple human cancers including colorectal, breast, histiocytomas, highly invasive glioblastoma, anaplastic astrocytomas, and metastatic melanomas." (PMID 26327620, 2015). "We also examined the effect of TGFβ on the expression of CD248 by normal and cancer associated fibroblasts (NF and CAF, respectively) that were derived from mouse mammary tissues." (PMID 24555435, 2014). "In this regard, we evaluated the relationship between the cytoplasmic domain of CD248 and SM22α, a tumor suppressor gene that when dysregulated, is implicated in the progression and metastasis of cancers of the colon, breast and prostate." (PMID 21549007, 2011). "Hence, we investigated the relationship between CD248 expression and cancer-associated fibroblasts (CAFs) infiltration in several cancers." (PMID 40276611, 2025). "Clinically, high CD248 expression is associated with poor survival in cancer patients." (PMID 40276611, 2025). "Notably, cancer cells and cancer associated fibroblasts are resistant to TGFβ mediated suppression of CD248." (PMID 24555435, 2014). "Notably, cancer associated fibroblasts (CAF) and cancer cells were resistant to TGFβ mediated suppression of CD248." (PMID 24555435, 2014). "In the violin plot of cancer staging, high expression of CD248 was significantly correlated with advanced stages of BLCA (P < 0.05), BRCA (P < 0.05), KIRP (P < 0.05), and KIRC (P < 0.05)." (PMID 40276611, 2025). "Significant efforts have been made to develop novel approaches to targeting CD248 for clinical cancer treatment, including the development of monoclonal antibodies, vaccines, radioimmunotherapy, antibody-drug conjugates (ADCs), and CAR-T." (PMID 40276611, 2025). "Conversely, CD248 expression is decreased in ten types of cancers, with the correlation between downregulated CD248 expression and BLCA, PRAD, SKCM, OV, and UCEC having been studied." (PMID 40276611, 2025). "By addressing these issues, CD248-targeted therapy has the potential to become a cornerstone of future cancer treatment." (PMID 40276611, 2025). "EPIC and TIDE algorithms showed that CD248 was correlated with CAFs infiltration in 40 types of cancers." (PMID 40276611, 2025). "In this study, bioinformatic analysis and in vitro experiments were used to determine the effect of CD248 on pan-cancer." (PMID 40276611, 2025). "Taken together, CD248 expression was significantly upregulated in several types of cancer, suggesting its potential role in cancer diagnosis and therapy." (PMID 40276611, 2025). "In conclusion, our findings identify CD248 as a potential prognostic and therapeutic biomarker in pan-cancer." (PMID 40276611, 2025).
cancer (continued). "This study aimed to investigate the expression patterns, genetic alterations, and functional networks of CD248 in pan-cancer, to elucidate the relationship between CD248 expression and patient prognosis, and to detect CD248’s role in immune cell infiltration." (PMID 40276611, 2025). "Four members compose the group XIV of CTLDcps: CD93, Clec14A, CD248, and Thrombomodulin, which have been studied extensively in human and mouse in the contexts of angiogenesis and cancer biology." (PMID 35659564, 2022). "Owing to its oncofetal gene-like expression pattern, targeting CD248 has been suggested for treating several disorders, such as tissue fibrosis and cancer." (PMID 36401329, 2022). "CD248 is an oncofetal protein-like molecule that has upregulated levels in many pathological conditions, including tissue fibrosis and cancer, and is widely expressed in the fetus during embryogenesis." (PMID 36401329, 2022). "Overall, the preceding findings indicate that the expression of CD248 in cancer cells is resistant to regulation by TGFβ." (PMID 24555435, 2014). "Mechanisms by which CD248 is downregulated are poorly understood, hindering the development of anti-cancer therapies." (PMID 24555435, 2014). "The physiologic importance of CD248 in cancer progression and its potential utility as a therapeutic target is further highlighted by the finding that lack of CD248 in mice results in resistance to the growth and metastasis of some tumors." (PMID 21549007, 2011). "The multiple pathways regulated by the cytoplasmic domain of CD248 highlight its potential as a therapeutic target to treat cancer." (PMID 21549007, 2011). "All these suggest the potential target therapy of CD248 in pan-cancer." (PMID 40276611, 2025). "Our study reveals that CD248 may function as a candidate biomarker for both prognosis and therapy in pan-cancer." (PMID 40276611, 2025). "CD248 expression is significantly increased in nine types of cancers in this study." (PMID 40276611, 2025). "All these findings indicated that CD248 may be a novel oncoprotein and a potential therapeutic target for pan-cancer." (PMID 40276611, 2025). "Some studies have shown that CD248 could regulate cell adhesion and metastasis in some other cancer types." (PMID 36997926, 2023). "Thus, synthetic peptides of active CD248 molecular decoys hold promise for treating cancer and fibrotic diseases." (PMID 36401329, 2022). "The group XIV of C-type lectin domain-containing proteins (CTLDcps) is one of the seventeen groups of CTLDcps discovered in mammals and composed by four members: CD93, Clec14A, CD248 and Thrombomodulin, which have shown to be important players in cancer and vascular biology." (PMID 35659564, 2022). "The antibody, antibody–drug conjugates (ADCs), vaccine, and even CAR-T cells targeting CD248+ CAFs might become promising strategies for the destruction of the cancer nest and overcoming the immunosuppressive TME." (PMID 34970489, 2021). "In another study, the preclinical efficacy of a novel antibody-drug conjugate, consisting of a humanized CD248 monoclonal antibody, hMP-E-8.3, conjugated to a potent duocarmycin derivative was tested in CD248 expressing cancer cell lines, and had specific, target-dependent killing activity." (PMID 30847027, 2019). "Thus, CD248 is a novel immunotherapeutic target for cancer treatment and using a translatable DNA-based immunotherapy." (PMID 30847027, 2019). "CD248 expression was assessed in 250 clinical human cancer specimens including 20 cancer subtypes." (PMID 30847027, 2019). "Recently, it has been shown that TGF-β strongly suppresses CD248 expression in healthy murine fibroblast cell lines; on the contrary, during cancer, where significantly higher CD248 levels are reported, mirroring what we observed in our cells, TGF-β failed to downregulate CD248 expression." (PMID 30285896, 2018).
cancer (continued). "CD248 was originally discovered as a human embryonic fibroblast specific antigen reactive to antibody Fb5 and was thought to be selectively expressed on the vascular endothelial cells of malignant tumors, thus named endosialin." (PMID 26327620, 2015). "Taken together, CD248 might be a novel candidate for targeted therapies in pan-cancer." (PMID 40276611, 2025). "Moreover, given CD248’s potential role in angiogenesis, the combination of immunotherapy and anti-angiogenic agents might offer a promising approach in cancer treatment in the future." (PMID 40276611, 2025). "CD248 plays a crucial role in HNSC functions, including invasion, migration, and proliferation, while its function in other cancers requires further experimental verification." (PMID 40276611, 2025). "We also analyzed expression of CD248 in different cancer types in TCGA, TARGET and GTEx databases, which showed that OS had obviously high CD248 expression." (PMID 36997926, 2023). "Notably, CD248 expression by cancer cells and cancer associated fibroblasts is not altered by TGFβ." (PMID 24555435, 2014). "Immunotherapies targeting CD248, including radioimmunotherapy, vaccines, ADCs, and CAR-T, could be effective treatments for cancer in clinical practice." (PMID 40276611, 2025). "In addition to specific antibody binding blockade, various novel immunotherapies including antibody drug conjugates (ADCs), cancer vaccines, and chimeric antigen receptor T (CAR T) cell therapy directed against CD248 have been explored." (PMID 38468017, 2024). "Based on our analyses, CM from CD248+CAFs or from CAFs‐sh‐CD248 with IL‐8 supplementation, and not from CAFs‐sh‐CD248, robustly protected cancer cell lines from chemotherapy‐triggered apoptosis." (PMID 38396325, 2024). "Other markers, like CD248 (endosialin, also known as tumor endothelium marker 1, TEM1) and CD90/THY-1, are highly expressed by PCs but also by pMSCs, especially in the context of cancer." (PMID 37686315, 2023). "Cd248, first identified in 1992 as the antigen for the FB5 antibody, has continued to interest investigators interested in the elucidation of disease mechanism(s) and as a therapeutic target in a wide variety of fibrotic conditions and cancer." (PMID 30847027, 2019). "Interestingly, CD248 could also bind with FN, collagen type I (Col I), IV (Col IV) and MMRN2 to promote the migration of cancer cells." (PMID 36997926, 2023). "While largely absent in normal tissues, CD248 is markedly upregulated in almost all cancers." (PMID 24555435, 2014).
infection (19 papers, 2010 to 2025). The state of being infected such as from the introduction of a foreign agent such as serum, vaccine, antigenic substance or organism. "Endosialin (CD248) positive TMCs play an essential role in revascularization during regeneration of the postnatal thymus after damage caused by infection." (PMID 35844535, 2022). "The expression profiles of zebrafish cd248 in response to LPS challenge, which mimics infection of pathogenic bacteria, were examined." (PMID 36119065, 2022). "CD248 is expressed on the mesenchymal stromal cells in thymus plays an important role in thymus development and thymus regeneration after infection, further participates in peripheral immunity." (PMID 36119065, 2022).
renal diseases (1 paper, 2025). "Immunohistochemical staining of CD248 revealed high expression in the mesangial area of DN tissues, whereas significantly reduced expression was observed in other kidney diseases." (PMID 40451785, 2025). "Recent studies have highlighted the significant role of CD248 in renal diseases." (PMID 40451785, 2025). "Clinical studies have suggested a potential role for CD248 in angiogenesis in kidney diseases." (PMID 40451785, 2025).
CD248 also shares sentences with these, for which no sentence is quoted: soft tissue sarcoma (7 papers); synovial sarcoma (4); brain cancer (3); adenocarcinoma (2); bacterial infection (2); colorectal tumor (2); Ewing sarcoma (2); gastric adenocarcinoma (2); lymphoma (2); metastatic disease (2); myxofibrosarcoma (2); rectal cancer (2); uterine sarcoma (2); abdominal aortic aneurysm (1); aneurysm (1); asthma (1); astrocytomas (1); bladder cancer (1); bone sarcoma (1); breast lobular carcinoma (1); cardiovascular diseases (1); cervical cancer (1); colon adenocarcinoma (1); diabetes (1); dilatation (1); endometrioid adenocarcinoma (1); esophageal adenocarcinoma (1); esophageal carcinoma (1); Glucose intolerance (1); gout (1).
A further 27 diseases each share a sentence with CD248 in 1 paper.